IFNG (interferon gamma)
Diseases named in the same sentence as IFNG in open-access papers (continued):
Sharing a sentence is not in itself a finding about the gene and the disease.
tuberculous pleurisy (26 papers, 2008 to 2022). "Summary of findings from studies evaluating pleural fluid adenosine deaminase (ADA) and unstimulated pleural fluid interferon-gamma (IFN-γ) for diagnosing pleural tuberculosis." (PMID 34166463, 2021). "Interferon gamma levels in pleural tuberculosis were significantly higher in both serum and pleural fluid of HIV-positive patients when compared with HIV-uninfected patients." (PMID 22474483, 2012). "Pooled results for accuracy of interferon-gamma assays to diagnose tuberculous pleurisy." (PMID 26038718, 2015). "Further improvements in the limit of detection of an ICT for IFNg, and possibly combination of IFNg with other biomarkers such as adenosine deaminase, are necessary for such a test to be of value in the evaluation of pleural tuberculosis." (PMID 24376880, 2013). "Therefore ADA analysis is more cost effective than the estimation of interferon gamma for the diagnosis of tuberculous pleuritis in developing countries." (PMID 18665218, 2008). "Tuberculous pleuritis usually presents as an acute illness with fever, cough and pleuritic chest pain, and is diagnosed by elevated levels of adenosine deaminase (ADA) and interferon-gamma (IFNγ) in the pleural fluid." (PMID 29101376, 2017). "Interferon gamma is considered to be a better marker than ADA for the diagnosis of tuberculous pleuritis, since its estimation is not affected by immununosuppression." (PMID 18665218, 2008).
acute kidney injury (25 papers, 2012 to 2025). Sudden and sustained deterioration of the kidney function characterized by decreased glomerular filtration rate, increased serum creatinine or oliguria. "Acute kidney injury was associated, and to a certain degree, predicted by IFNg, TWEAK, MMP7, and MUC-16." (PMID 34608231, 2021). "CRRT with the oXiris filter seemed to allow effective removal of endotoxin and TNF-α, IL-6, IL-8 and IFNγ in patients with septic shock-associated acute renal failure." (PMID 31369593, 2019). "IL-18 (known as an interferon-gamma (IFN-γ) inducing factor), and other inflammatory cytokines have important roles in lipopolysaccharide (LPS)-induced acute kidney injury (AKI)." (PMID 29261164, 2017). "All-in-all, our analysis does not point to the cytokines IL6, IFNγ and TNFα, that have classically been associated with low grade inflammation in cardiovascular disease and renal failure." (PMID 22957013, 2012).
chronic kidney disease (25 papers, 2012 to 2025). Impairment of the renal function secondary to chronic kidney damage persisting for three or more months. "In the other two papers, monocytes gene expressions in CKD and end-stage renal disease patients showed induction of the so-called suppressors of cytokine signaling, which modulate the Jak/Stat transcription pathway and steer the actions of IFNγ and IL6." (PMID 22957013, 2012).
coccidiosis (25 papers, 2018 to 2025). A parasitic infection caused by Coccidia. "This work also demonstrated that a methanolic extract of B. pilosa enhanced immunity through the increased expression of interferon-gamma (IFN-γ) in T cells isolated from chicken cecal tonsils, which are important components of host immunity against coccidiosis." (PMID 37242733, 2023). "Studies demonstrated that interferon gamma levels increase during coccidiosis and that this molecule plays a particular role in the activation of intracellular toxicity via free radical generation and decreasing oocyst production during primary infection with Eimeria spp." (PMID 31297194, 2019). "Interferon gamma plays a critical role in mediating protective immunity against coccidiosis." (PMID 31297194, 2019).
eczema (25 papers, 2010 to 2025). "Eczema was associated with decreased concentrations of IFNα, IFNγ, TSLP, CXCL9, and CXCL13, but increased concentrations of CCL18 and Galectin-3." (PMID 31998285, 2019). "Lastly, PHF11, a transcriptional activator of the Th1 effectors interleukin-2 (IL2) and interferon-γ (IFNG), is predicted to be associated to eczema." (PMID 28598986, 2017). "In addition, eczema was associated with decreased concentrations of IFNα, IFNγ, TSLP, CXCL9, and CXCL13, but with increased concentrations of CCL18 and Galectin-3." (PMID 31998285, 2019). "Early phase acute AD (aAD) is characterized by erythema, eczema, and pruritus, all caused by a predominant TH2-mediated immune response via increased production of interleukin (IL)-4, IL-5, and IL-13, and a decrease in production of IL-12 and interferon-gamma (IFN-γ)." (PMID 38582857, 2024).
intestinal infection (25 papers, 2012 to 2024). "IFNγ plays a primordial role in immune cells to fight intestinal infections: it activates macrophages and Th1 expansion, which induces an effective immune response against pathogens." (PMID 30420848, 2018). "IFNγ-producing regulatory T cells have been described in the setting of intestinal infection and allograft rejection and evidence suggests a central role of IFNγ in inducible TReg cell generation." (PMID 22666318, 2012). "It is also noteworthy that enteric MHV infection of B cell deficient mice causes a more prolonged intestinal infection, while the same virus in T cell deficient mice causes an FIP-like disease like what occurs when systemic MHV is inoculated into IFNγ deficient mice." (PMID 30086792, 2018).
liver cirrhosis (25 papers, 2008 to 2025). "Additional experiments demonstrating the impact of IFNγ on TNFα and IL-6 production by CD14positive myeloid ascites suggested that NK cells might have indeed a regulatory role during peritonitis in patients with liver cirrhosis." (PMID 31440239, 2019). "Furthermore, following stimulation with IL-12 + IL-18, the expression of IFNγ and TNFα was reduced in CD8+ T cells from compensated liver cirrhosis in comparison with healthy controls." (PMID 41028194, 2025).
myositis (25 papers, 2013 to 2026). "For instance, higher baseline levels of IL-12p70 and leukemia inhibitory factor (LIF) are associated with myositis, granulocyte-macrophage colony-stimulating factor is linked to rash, and interferon-gamma (IFN-γ) is relevant to various irAEs." (PMID 38183211, 2024). "Importantly, these interactive cellular networks culminate in a TH1 driven, pro-inflammatory cascade (marked by upregulation of genes encoding the TH1-associated cytokines IFNγ, TNFα, and IL-1β) that steers the disease process away from fibrosis and defines the myositis phenotype in WT mice." (PMID 37809058, 2023). "IFNs, widely implicated in human IIMs, and particularly IFNγ, also involved in Icos-/- NOD mice myositis, appear to play a central role in this process." (PMID 38926363, 2024). "By means of transcriptome data analysis of muscle biopsies from patients with DM, and in vitro studies of human myoblasts exposed to IFNγ, we confirmed the correlation between this cytokine and mitochondrial anomalies in human myositis." (PMID 38926363, 2024). "Here, we examine the role of interferon γ (IFNγ) using NOD female mice deficient in the inducible T cell co-stimulator (Icos), which have previously been shown to develop spontaneous IFNγ-driven myositis mimicking human disease." (PMID 38926363, 2024). "Taken together, our results suggest that in myositis muscle, IFNγ coordinates the local overexpression of complement genes that occurs in several cell types." (PMID 36739295, 2023). "In this study, bulk RNA sequencing (RNAseq) analyses of muscle biopsy specimens revealed that complement genes are locally overexpressed and correlate with markers of myositis disease activity, including the expression of interferon-gamma (IFNγ)-induced genes." (PMID 36739295, 2023). "Interferon alpha (IFN-α), interferon gamma (IFN-γ), tumor necrosis factor alpha (TNF-α), and IL-1α/β are up-regulated in the muscle of myositis patients, which is implicated in the mediation of Th1 and pro-inflammatory responses." (PMID 26417430, 2015). "These therefore confirm that IFNγ exerts a negative effect on human muscle and a pathogenic role in myositis as in mice." (PMID 38926363, 2024). "Furthermore, we found that exposure of differentiating human myoblasts to IFNγ reduced the expression of OXPHOS genes and altered mitochondrial ultrastructure, confirming IFNγ-driven mitochondrial alterations in myositis." (PMID 38926363, 2024). "This suggests that the overexpression of complement genes in patients with myositis is not only due to an increased number of cells expressing complement, but also the result of a more intense expression in each of those cells induced by IFNγ." (PMID 36739295, 2023). "Although both types of interferons may induce PSMB8/-9, in myositis muscle transcriptomes only IFNγ was significantly increased with dominance in IBM (74% increased change call, 4.9-fold increased) and correlated with PSMB8/-9." (PMID 25098831, 2014). "Collectively, these analyses demonstrate that a combination of innate and adaptive immune signals leads to activation of IFNγ-producing TH1 cells (marked by preferential expression of Tbet in muscle-infiltrating T cells of WT mice) as key drivers of the inflammatory process in HRS-induced myositis." (PMID 37809058, 2023). "Previous studies have also shown elevated muscle levels of numerous cytokines associated with type 1 inflammation, including CCL5, CXCL9, CXCL10, CXCL11, IFNG, and TNF in IBM patients compared to various myositis and non-myositis controls." (PMID 40034760, 2025). "We next aimed at dissecting the bi-directional association between mitochondrial dysfunction and inflammation by studying the effects of IFNγ-blocking and ROS-buffer therapy on Icos-/- NOD myositis." (PMID 38926363, 2024).
myositis (continued). "Despite we observed a generalized overexpression of PSMB8, whose transcription has been associated to type-II IFN exposure, in all three comparisons between myositis and NDC conditions, IFNG was downregulated in DM compared to NDC and upregulated in irMyositis compared to DM." (PMID 40759686, 2025). "There were limitations to this study due to the short time period of IL-1β and IFNγ exposure considering the progressive, chronic nature of myositis conditions, as well as a lack of investigation of different IL-1β and IFNγ concentrations." (PMID 37731843, 2023). "As IFNγ is also secreted in IIM, the immunoproteasomal system may also contribute to pathomechanisms in myositis." (PMID 25098831, 2014). "This may be induced by misfolded protein from fiber degradation or suspected retroviral or viral triggers in this type of myositis and thereby contribute to CD8+ T-cell triggering, expansion and IFNγ production." (PMID 25098831, 2014). "In this study, we could identify in the myositis transcriptomes only IFNγ but not IFNα as a predominant trigger for PSMB8/-9, which also correlated with the expression of STAT1 and IRF-1." (PMID 25098831, 2014).
pertussis (25 papers, 2010 to 2025). A contagious bacterial respiratory infection caused by Bordetella pertussis. "The whole-cell pertussis vaccinations were characterized by an elevated production of T-helper cell type 1 cytokines, such as IFNγ or IL-2." (PMID 37574522, 2023). "We also found that IFNγ responses in response to pertussis antigen re-stimulation were enhanced in the BCG-trained cohort." (PMID 35177621, 2022). "Subjects in the BCG-trained cohort also displayed elevated IFNγ secretion in response to stimulation with all three pertussis antigens." (PMID 35177621, 2022). "Overall these results highlight that trained immunity-associated cytokine responses 3 months after BCG vaccination are correlated with increases in pertussis-specific antibody responses and IFNγ production, as well as total IgG-switched MBC responses." (PMID 35177621, 2022). "We plotted the epitope-specific IFNγ/IL-13 responsiveness of individual pertussis patients (with an epitope proliferative response of S.I. ≥2) against time elapsed since diagnosis grouped as Prn peptide responses or grouped as Ptx peptide responses." (PMID 24391789, 2013). "We found that the BCG-trained cohort displayed augmented IFNγ in response to pertussis antigen re-stimulation, which is a readout for Th1 immunity, and may therefore suggest improved clinical protection against pertussis." (PMID 35177621, 2022). "Th1 and Th17 T-cell responses against pertussis antigens were measured by stimulating peripheral blood mononuclear cells (PBMCs) with either PRN, PT, or FHA for 7 days and measuring secreted IFNγ, IL-22, and IL-17 by ELISA26." (PMID 35177621, 2022). "Furthermore, increases in pertussis antibodies, total IgG-switched MBC responses, and IFNγ in response to PT restimulation in the BCG-trained cohort were associated with innate responses, in particular IL-1β and IL-6." (PMID 35177621, 2022). "To determine the impact of age on functionality of Bp-specific responses, we studied IFNγ responses in early and late phase post-infection PBMC samples from youngsters and adult pertussis patients of the SKI cohort with a similar whole cell pertussis vaccine priming background." (PMID 35822011, 2021).
Q fever (25 papers, 2011 to 2025). A bacterial infection caused by Coxiella burnetii. "Multiple studies in murine models of Q fever have shown that IFNγ knock-out or T-cell deficient animals control C. burnetii infection very poorly, highlighting the essential role of these specific cellular responses." (PMID 35812430, 2022). "Two recent studies genotyped human populations and revealed that genetic variation in innate immune genes, such as those encoding pattern recognition receptors and IFNG, are associated with susceptibility to Q fever." (PMID 33789347, 2021). "For example, in mycobacterial infections, IL6 expression can also alter or hinder IFNγ production, consequently resulting in Q-fever." (PMID 38391673, 2024). "A study of mostly elderly individuals who were offered Q-VAX® after the Dutch Q fever outbreak found that pre-vaccination C. burnetii-specific IFNγ responses correlated with local reactions after skin test." (PMID 35812430, 2022). "Blood mononuclear cells of patients with chronic Q fever, when exposed to C. burnetii in vitro, produce high amounts of Interferon-gamma (IFNg), the proinflammatory cytokine considered crucial for killing of the pathogen." (PMID 35137689, 2022). "Altogether, these data indicate that IFNγ responses are a more sensitive and durable marker of exposure to Q fever than are serological responses." (PMID 34394097, 2021). "Directed studies in humans reveal that single-nucleotide polymorphisms (SNPs) in innate immune receptors and signaling genes such as TLR1, STAT1, IFNG, and MYD88 are associated with acute or chronic Q fever." (PMID 33789347, 2021). "Recruited subjects were categorized based on clinical Q fever history and recall responses to heat-killed C. burnetii in a whole blood IFNγ release assay (IGRA)." (PMID 30828331, 2019). "Using this systematic approach, we successfully identified a set of epitopes that recalls long-term memory IFNγ T-cell responses in humans and thus represents a promising first step in the development of a T-cell based human multi-epitope Q fever vaccine." (PMID 30828331, 2019). "It is of interest though that we do see somewhat higher IL-2 responses and a lower IFNγ/IL-2 ratio in the asymptomatic Q fever seropositive control group of our study." (PMID 29804281, 2018). "Studies of Dutch Q fever patients and vaccinees suggest that ex vivo measurement of interferon gamma (IFNγ) release by circulating immune cells in response to stimulation by whole cell antigen can provide a sensitive assessment of cell-mediated immune memory responses to Cb." (PMID 40573946, 2025). "Interestingly, chronic Q fever is distinguished by high circulating levels of IFNγ and a high IFNγ/IL-2 ratio." (PMID 40435199, 2025). "In this study, we assessed the performance of a whole blood C. burnetii IFNγ release assay in comparison to serological detection in an area of high Q fever incidence in 2014, up to seven years after initial exposure during the Dutch Q fever outbreak 2007-2010." (PMID 34394097, 2021). "In addition to antimicrobial and surgical treatment, immunomodulatory agents including interferon gamma were found to be effective in vitro and in some case reports of chronic Q fever." (PMID 32818415, 2020). "Subjects were divided into three groups: controls with no immunological evidence of previous infection and individuals with responses to heat-killed C. burnetii in a whole blood IFNγ release assay (IGRA) who remained asymptomatic or who experienced clinical Q fever during the outbreak." (PMID 30828331, 2019). "Therefore, although IFNγ responses appear similar between patients with persistent complaints and asymptomatic Q fever seropositive controls in our study, there are several factors that are likely to influence this observation." (PMID 29804281, 2018).
Q fever (continued). "It was also shown that antigen-specific IFNγ production is a useful tool for diagnosing a previous Q fever infection, and adding antigen-specific IL-2 production helped discriminate chronic Q fever patients from Q fever seropositive controls and QFS patients." (PMID 29804281, 2018). "We did show that it may be possible to discriminate QFS patients with persistent complaints from recovered QFS patients, with the latter showing lower antigen-specific IFNγ production than the former, even surpassing asymptomatic Q fever seropositive controls." (PMID 29804281, 2018). "The C. burnetii-specific whole-blood interferon-γ (IFNγ) production assay showed promising results in differentiating QFS patients from Q fever seropositive controls and further implementation of an IFNγ/interleukin-2 (IL-2) ratio helped differentiate QFS patients from chronic Q fever patients." (PMID 29804281, 2018). "Recent studies have investigated interferon-gamma (IFN-γ) based assays, including a whole-blood IFN-γ production assay and a Coxiella enzyme-linked immunospot (Coxiella ELISPOT), as potential diagnostic tools for Q fever diagnosis." (PMID 25084353, 2014). "Notably, the effect of deletion of Acod1 on C. burnetii replication was much stronger than the impact of deficiencies of several other IFNγ‐induced antimicrobial defense mechanisms (NOS2, IDO1/2, GBPs), thus establishing ACOD1 as a major protective determinant in the host defense against Q fever." (PMID 36479617, 2023). "Moreover, C. burnetii-specific IFNγ responses were found to be more durable than antibody responses in two sub-groups of individuals known to have sero-converted by 2007 or previously reported to the municipality as notified Q fever cases." (PMID 34394097, 2021). "Moreover, C. burnetii-specific IFNγ responses were found to be more durable than antibody responses in two sub-groups of individuals known to have sero-converted as of 2007 or previously reported to the municipality as notified Q fever cases." (PMID 34394097, 2021). "We start by comparing antigen-specific whole-blood IFNγ and IL-2 production in QFS patients who have recovered from their complaints, QFS patients who have persisting complaints, and asymptomatic Q fever seropositive controls." (PMID 29804281, 2018). "Previously, our group showed that antigen-specific IFNγ production was significantly higher in QFS patients (n = 28; 319.4 pg/mL) than in Q fever seropositive controls (n = 135; 120 pg/mL)." (PMID 29804281, 2018). "In order to better understand the kinetics of antigen-specific IFNγ production in QFS patients and asymptomatic Q fever seropositive controls, we suggest measuring IFNγ production longitudinally, starting at the time of infection." (PMID 29804281, 2018). "In addition, after stimulation with C. burnetii antigens, monocytes from Q fever patients produced PGE2, which in turn downregulated T lymphocyte-mediated IL-2 and IFNγ production." (PMID 29390006, 2018). "In this study, antigen-specific IFNγ production was not significantly higher in QFS patients than in asymptomatic Q fever seropositive controls." (PMID 29804281, 2018).